MTOR (mechanistic target of rapamycin kinase)
Diseases named in the same sentence as MTOR in open-access papers (continued):
Sharing a sentence is not in itself a finding about the gene and the disease.
myocarditis (10 papers, 2018 to 2026). Myocarditis is a condition that is characterized by inflammation of the heart muscle (myocardium). "Another study showed that MSC-Exo activated AMPK/mTOR signaling to mediate the autophagy flux pathway in alleviating CVB3 virus-induced myocarditis." (PMID 39769256, 2024). "HucMSC-Exo also alleviated virus-induced myocarditis by activating the AMPK/mTOR-mediated autophagy pathway to reduce cardiomyocyte apoptosis." (PMID 39769256, 2024). "By analyzing coexpressed proteins, we found four hub proteins that may lead to the occurrence of ICI-related myocarditis, mammalian target of rapamycin (mTOR), GSK3β, PTPN11, and MFN2." (PMID 36760573, 2023). "By combining PD-L1-related proteins, we found that mTOR, GSK3β, PTPN11, and MFN2 may be potential diagnosis and treatment biomarkers of ICI-associated myocarditis." (PMID 36760573, 2023). "In summary, this study demonstrated that hucMSC‐exosomes could exert the partially protective effects on CVB3‐induced myocarditis by activating AMPK/mTOR‐mediated autophagy flux pathway to attenuate cells apoptosis." (PMID 32424968, 2020). "Second, we confirmed that mTOR, GSK3β, PTPN11 and MFN2 are highly expressed in ICI-related myocarditis by proteomic sequencing, cellular experiments are required to verify our hypothesis." (PMID 36760573, 2023). "In conclusion, hucMSC‐exosomes could alleviate CVB3‐induced myocarditis via activating AMPK/mTOR‐mediated autophagy flux pathway to attenuate cardiomyocyte apoptosis, which will be benefit for MSC‐exosome therapy of myocarditis in the future." (PMID 32424968, 2020). "Here we investigated the cardioprotective effect of the CPCs-Ex for myocardial cells in CVB3-induced myocarditis model, which is mainly through abrogating the CVB3 proliferation as well as regulating the expressions of mTOR signaling pathway and Bcl-2, caspase families." (PMID 31534118, 2019).
nephritis (10 papers, 2008 to 2025). Inflammation of renal tissue. "Beneficial effects of mTOR inhibitors were also reported in anti-thy1 nephritis, in experimental membranous nephropathy, in adriamycin induced nephropathy, in unilateral obstructive uropathy and in the murine model of renal polycystic disease." (PMID 22427849, 2012). "Network analysis showed that many of these nephritis genes are known to interact with the mTOR pathway." (PMID 18980674, 2008). "Using curated findings from the literature, the shortest path for about one sixth of the 387 nephritis genes was defined to be either 0 or one-step downstream of the rapalog-mTOR pathway." (PMID 18980674, 2008). "We suggested that mTOR signaling might play an important role in the initiation and progression of kidney inflammation." (PMID 22470459, 2012). "Therefore, based on curated protein-protein and drug-protein interactions in the literature we determined that about 15% of the identified 387 nephritis genes interact with components of the rapalog-mTOR pathway." (PMID 18980674, 2008). "Our comprehensive analysis of the effects of 1.25(OH)2D3 on renal histopathology, mTOR protein, and PCNA in rat nephritis models showed that the grading of pathological renal damage, PCNA expression, and mTOR expression were positively correlated (p <0.05)." (PMID 39636964, 2024). "In this study, we established Thy-1 rat nephritis models and administered 1.25(OH)2D3 and rapamycin to the experimental groups to observe changes in PCNA and mTOR expression in rat renal tissues at different time points." (PMID 39636964, 2024). "We demonstrated neutralizing IGFBP2-downregulated CD4+ T cell activation, upregulated the ratio of Treg, downregulated AKT/mTOR/4E-BP1 pathway, and significantly improved nephritis in MRL/lpr mice." (PMID 36008635, 2022). "Increased mTOR phosphorylation at Ser2448, but not at Ser2481, and ERK phosphorylation were observed in the glomeruli of NZBWF1/J mice with active nephritis." (PMID 35571122, 2022).
pancreatic neuroendocrine neoplasm (10 papers, 2014 to 2025). A neoplasm with neuroendocrine differentiation that arises from the pancreas. "Higher expression of phospho-mTOR, the activated form of the mTOR, has been shown to correlate with liver recurrence and a worse survival in patients undergoing radical surgery for pancreatic NENs." (PMID 36980746, 2023). "It epigenetically promotes tumor cell proliferation in pancreatic neuroendocrine neoplasms by inhibiting the tumor suppressor p57Kip2 and the mTOR pathway." (PMID 27835598, 2016). "Our data identifies that NAP1L1 epigenetically promotes tumor cell proliferation in pancreatic neuroendocrine neoplasms through inhibition of the mTOR pathway and the tumor suppressor p57Kip2; the principal mechanism is via p57Kip2 promoter methylation." (PMID 25071868, 2014). "Prdx2 may suppress the growth of pancreatic neuroendocrine neoplasms and could be a marker for predicting the efficacy of mTOR inhibitors." (PMID 33182509, 2020). "Studies have shown that in pancreatic neuroendocrine neoplasms, FABP5 activates the PI3K/Akt/mTOR signalling pathway, leading to enhanced lipid metabolism and cellular proliferation." (PMID 39928282, 2025). "In pancreatic neuroendocrine neoplasms, NAP1L1 promotes tumor cell proliferation and regulates cell entry into the S phase via inhibition of the mTOR pathway." (PMID 35351053, 2022). "Other therapeutic options include biologic agents interfering with specific molecules of cell signaling pathways, e.g., the mammalian target of rapamycin (mTOR) and vascular endothelial growth factor (VEGF), with everolimus and sunitinib, respectively, both approved for pancreatic NENs." (PMID 31467527, 2019).
primary immunodeficiency (10 papers, 2016 to 2025). "Hcrt expression showed significant correlations with the “ErbB signaling pathway,” “insulin signaling pathway,” “mTOR signaling pathway,” and “primary immunodeficiency,” among others." (PMID 40166636, 2025). "In addition, cell cycle, DNA replication, insulin signaling pathway, MTOR signaling pathway, natural killer cell-mediated cytotoxicity, primary immunodeficiency, TGF beta signaling pathway, and WNT signaling pathway might be the main pathways regulated by CDC20." (PMID 35800227, 2022). "In KEGG pathway analysis, intestinal immune networks for IgA production, primary immunodeficiency, ERBB signaling pathway, MTOR signaling pathway, WNT signaling pathway, etc. were identified for the 5-PIDElncRNA signature." (PMID 34368371, 2021). "GSVA analysis showed that pathways enriched in high-risk subgroup included signalling pathways such as TGF-β, WNT, mTOR, Notch and MAPK, while pathways such as DNA replication, proteasome, primary immunodeficiency and antigen processing and presentation were enriched in the low-risk subgroup." (PMID 38057405, 2023).
PTEN hamartoma tumor syndrome (10 papers, 2019 to 2024). An autosomal dominant syndrome caused by pathogenic variants in the PTEN gene, characterized by hamartomas, overgrowth, neurodevelopmental disorders and an increased risk of various cancers, including breast, thyroid, and endometrial cancer. "PTEN is very similar to TSC1/2 in that it is also an upstream negative regulator of mTOR, and heterozygous variants lead to PTEN Hamartoma Tumor Syndrome (PHTS)." (PMID 39881808, 2024). "One of the important pathophysiological conditions associated with the hyperactive PI3K/AKT/mTOR axis is deficient PTEN function such as is observed in PTEN-deficient cancer cells or lipoma cell cultures derived from PTEN hamartoma tumor syndrome (PHTS) patients." (PMID 31856761, 2019). "With regard to the PI3K/mTOR pathway genes, PTEN pathogenic variants have been an established cause of PTEN hamartoma tumor syndrome (PHTS; MIM 158350), also known for many years as Bannayan-Riley-Ruvalcaba syndrome in childhood." (PMID 31555216, 2019). "mTOR inhibitors derived from rapamycin, namely everolimus and temsirolimus, have been used for the treatment of tuberous sclerosis complex-associated angiomyolipomas (MIM: 191100) and PTEN hamartoma tumor syndrome (PHTS; MIM: 601728) but with mixed results." (PMID 38141607, 2024). "A deficiency in functional PTEN due to heterozygous germline mutations leads to a constant activation of PI3K/AKT/mTOR signaling, causing a number of disorders, which are summarized as PTEN hamartoma tumor syndrome (PHTS)." (PMID 36077184, 2022).
renal dysfunction (10 papers, 2014 to 2024). "The switch from CNI to mTOR inhibitor in the early phase after LT might alleviate deterioration of the renal function in recipients who are identified as being at a high risk for developing renal dysfunction after LT." (PMID 37264212, 2023). "In our current practice, in patients with renal dysfunction risk factors, we reduced the CNI dosage and administered an mTOR inhibitor early to prevent renal function deterioration." (PMID 37077866, 2023). "In patients with renal dysfunction (n = 13), a combination of low-dose CsA and the mTOR inhibitor everolimus was initiated." (PMID 31407088, 2019). "The adverse events (AEs) leading to treatment discontinuation included gastrointestinal perforation, renal dysfunction, perianal abscess, diarrhea, hyponatremia and hoarseness due to axitinib, dermatitis, stomatitis, and skin rash due to mTOR inhibitors." (PMID 30651932, 2018). "Renal dysfunction was more commonly observed in the mTOR inhibitors and TKIs polytherapy compared to either monotherapy, whereas proteinuria occurred at a similar rate in the combination of mTOR inhibitors and TKI compared to the TKI monotherapy." (PMID 38989147, 2024).
vascular dementia (10 papers, 2019 to 2025). A degenerative vascular disorder affecting the brain. "Treatment with everolimus in mice with bilateral common carotid artery stenosis, a vascular dementia model that induces mTOR activation, also caused a shift toward anti-inflammatory microglia due to a loss of inhibitory feedback of mTORC1 on PI3K, alternatively activating the prosurvival kinase Akt." (PMID 33041976, 2020). "The results of our study showed that the mRNA expression of PI3K, Akt, and mTOR in the hippocampus of the vascular dementia rats, were significantly decreased." (PMID 36767264, 2023). "This process was closely related to aerobic exercise regulating the autophagy signaling pathway PI3K/Akt-mTOR, to improve hippocampal nerve apoptosis in vascular dementia rats." (PMID 36767264, 2023). "Other studies have used brain injuries, such as stroke or vascular dementia in combination with mTOR blockage to evaluate microglial changes." (PMID 33041976, 2020). "Li’s research on a vascular dementia model demonstrated that atorvastatin could reduce memory loss by influencing neuronal apoptosis and autophagy-related pathways, as well as activating the AMPK/mTOR signaling pathway, thereby attenuating learning and memory impairments." (PMID 40129866, 2025).
adrenocortical tumors (9 papers, 2012 to 2025). "miR-99a-5p and miR-100-5p are downregulated in childhood adrenocortical tumors and repress the proliferation of both adrenocortical tumors and pediatric adrenocortical carcinoma cells by targeting mTOR, RAPTOR, and IGF1R." (PMID 40161350, 2025). "In childhood adrenocortical tumors, miR-99a and miR-100 directly target mTOR 3′-UTR, and the inhibition of mTOR signaling by Everolimus greatly attenuates tumor cell growth in vitro and in vivo." (PMID 25141911, 2014). "A recent study demonstrated that pharmacologic inhibition of mTOR signaling by everolimus greatly reduced adrenocortical tumor cell growth both in vitro and in vivo, also confirming the importance of microRNA regulation of IGF-2/mTOR signalling cascade." (PMID 22934112, 2012). "Consistent with a recent study showing that miR-99a directly targets and regulates mTOR in childhood adrenocortical tumors, we found that forced expression of miR-99a suppressed luciferase activity of the wild type, but not the mutant mTOR reporter and mTOR expression at protein level." (PMID 23762265, 2013). "Everolimus (Eve) acts on mammalian target of rapamycin (mTOR), a key component of the PI3K/Akt pathway, and its antiangiogenic activity and antitumor effects have been reported in adrenocortical tumors." (PMID 29507530, 2018).
Alcoholism (9 papers, 2015 to 2025). "Studies have shown that inhibition of the AKT/mTOR pathway can activate autophagy and mitophagy, thereby alleviating UV-induced skin photoaging and hepatocyte senescence in alcoholic fatty liver mice." (PMID 39044215, 2024). "By contrast, we identified significant enrichment in three pathways (mTOR signaling, axon guidance, and alcoholism) that are commonly affected by the gene regulatory mechanisms associated with all four phenotypes." (PMID 32391060, 2020). "The mTOR signaling pathway (hsa04150), axon guidance (hsa04360) and alcoholism (hsa05034) pathways contain eGenes whose regulation is associated with genetic variants from each of the four phenotypes." (PMID 32391060, 2020). "Leucine-enriched BCAA supplementation has been reported to restore impaired mTOR signaling and increase autophagy, leading to reduced muscle breakdown in patients with alcoholic LC." (PMID 33050430, 2020). "In addition, the 7 KEGG pathways include the “ AMPK signaling pathway”, “ mTOR signaling pathway”, “ ErbB signaling pathway”, “ Antigen processing and presentation “, “ Cocaine addiction”, “ Nucleocytoplasmic transport “, and “Alcoholism”." (PMID 41438739, 2025). "Therefore, we designed an IL-37d recombinant protein with a cell-penetrating TAT polypeptide to stress its intracellular role in suppressing Rheb-mTORC1 axis and evaluated its therapeutic effects on alcohol-induced mTOR overactivation." (PMID 38907105, 2024). "Subsequently, KEGG results figured out enrichment pathways consisting of HPV infection, viral carcinogenesis, alcoholism, osteoclast differentiation, transcriptional misregulation in cancer, mTOR and PI3K-AKT signal pathway, as well as other cancer-related pathways." (PMID 36734243, 2023). "Similar patterns were observed in both the mTOR signaling and alcoholism pathways." (PMID 32391060, 2020). "Notably, while there were no eGenes that were shared by all four phenotypes, there were three pathways (i.e., axon guidance, alcoholism and the mTOR signaling pathway) that contained co-occurring eGenes from all four conditions." (PMID 32391060, 2020).
B-cell acute lymphoblastic leukemia (9 papers, 2015 to 2024). A neoplasm of lymphoblasts committed to the B-cell lineage, typically composed of small to medium-sized blast cells. "Several transcription factors increase mTOR transcription including sirtuin 1 (SIRT1), myeloid zinc finger 1 (MZF1), and Nrf2 while Ikaros represses mTOR transcription in B cell acute lymphoblastic leukemia." (PMID 38270460, 2024).
chronic atrophic gastritis (9 papers, 2015 to 2025). Atrophic gastritis that is persistent and long-standing. "In an independent series, stronger expression of pS6K1 (a direct target of mTOR) was associated with the resistant group and morphologic evidence of active gastritis was associated with the sensitive group." (PMID 34913612, 2022). "In addition, gastritis was significantly relieved in mTOR knockout (KO) mice which infected with H. pylori." (PMID 35463631, 2022). "TCM prescriptions have been reported to effectively intervene in PLGC (including chronic atrophic gastritis [CAG], GIM, and dysplasia) via the PI3K/Akt/mTOR or EGFR/PI3K/Akt pathways." (PMID 38096029, 2023). "These complementary approaches then suggested active gastritis, which correlates with TLR5, and phosphorylated S6K1, a substrate of mTOR, as the most practical surrogate markers for responses to H. pylori eradication therapy." (PMID 34913612, 2022). "In the third step, we showed active gastritis and phosphorylated S6K1 as surrogate markers for TLR5 and mTOR, respectively." (PMID 34913612, 2022).
Down syndrome (9 papers, 2017 to 2025). "mTOR signaling positively regulates mGluR mediated long-term synaptic activity and mushroom-shaped dendritic spines in the hippocampus in a Down’s syndrome rodent model." (PMID 36674893, 2023). "Treatment with mTOR inhibitors or PI3Kδ inhibitors for patients with Down syndrome should be explored in future research, but only if justified by the clinical severity of the associated complications." (PMID 35222360, 2022). "Stimulation of mTOR signalling has been observed in response to accumulation of Aβ, and hyperactivation of mTOR is observed in Down's syndrome (in which the dosage of the APP gene is increased because it resides on chromosome 21 and early-onset AD is common)." (PMID 34842276, 2022). "Hyperactivation of the PI3K/Akt/mTOR pathway was also observed in autopsy samples of patients with Down syndrome compared with controls." (PMID 28288694, 2017). "The mTOR activity of dendrites in the hippocampus has been shown to be increased in a mouse model of Down syndrome." (PMID 28288694, 2017). "A mouse model of Down syndrome demonstrated that protein oxidation was increased possibly due to the decreased protective effect of autophagy as a result of mTOR pathway hyperactivation." (PMID 28288694, 2017). "Down syndrome is characterized by abnormalities in dendritic morphology and synaptic plasticity, and mTOR is believed to be involved in the growth and branching of dendrites in the hippocampus." (PMID 28288694, 2017). "The cognitive and functional decline may reflect an early-onset neurodegenerative process that may be secondary to abnormal MTOR activation, as seen in Alzheimer-like dementia in Down syndrome." (PMID 34197453, 2021). "Mammalian target of rapamycin (mTOR) signaling is aberrant and hyperactive in Down syndrome and AD." (PMID 33233734, 2020). "However, oxidative stress secondary to trisomy 21, including duplication of the gene encoding Cu/Zn-superoxide dismutase, contributes to Down syndrome symptoms and complicates its prognosis through activation of pathways such as AGE-RAGE and mTOR and inhibition of autophagy." (PMID 40356974, 2025).